CCR4 (C-C motif chemokine receptor 4)
Diseases named in the same sentence as CCR4 in open-access papers (continued):
Sharing a sentence is not in itself a finding about the gene and the disease.
colorectal cancer (17 papers, 2014 to 2025). A primary or metastatic malignant neoplasm that affects the colon or rectum. "High CCR4 expression in colorectal cancer tissues has been associated with shorter overall survival and enhanced metastasis, emphasizing its relevance as a homing marker for targeted therapies." (PMID 38254876, 2024). "Enhanced infiltration of CCR4+ Treg cells has been associated with unfavorable prognoses in different cancer types, including pancreatic ductal adenocarcinoma, prostate cancer, and colorectal cancer." (PMID 37842637, 2023). "Nevertheless, little is known about the role of CCR4 itself in the progression of colorectal cancer." (PMID 27356745, 2016). "For example, CCR4 is controlled by NFκB in colorectal cancer, promoting its metastasis." (PMID 35222362, 2022). "CCR4-mediated MMP13 activity in colorectal cancer cells requires NF-κB." (PMID 30140381, 2018). "Although CCR4 did not represent an independent risk factor for patients with colorectal cancer, these results still showed a critical role of CCR4 in colorectal cancer." (PMID 27356745, 2016). "As a crucial chemokine receptor for mediating immune homeostasis, however, the role of CCR4 in colorectal cancer (CRC) remains unknown." (PMID 27356745, 2016). "This seems to be supported by the fact that the matrix-metalloproteinase 13 (MMP13) is induced by CCR4 in an ERK/NFκB-dependent manner, facilitating invasiveness or migration of colorectal cancer cells through CCR4/CCL17-mediated Rho-kinase signaling." (PMID 30053879, 2018). "CCR4 is also expressed by non-lymphoid solid tumors such as breast, lung and colorectal cancer as well as by hepatocellular carcinoma." (PMID 28415693, 2017). "In the present study, we demonstrated that NF-κB but not β-catenin or Runx2, modulated the CCR4-mediated MMP13 activity in colorectal cancer cells, suggesting a crucial function of NF-κB in regulating invasiveness of tumor cells." (PMID 27356745, 2016). "In addition, CCR4 has been reported to aggravate tumor malignancy and facilitate tumor metastasis through activation of ERK signaling in bladder cancer, hepatocellular carcinoma and colorectal cancer." (PMID 39473097, 2025). "Besides, literature reports that CCR4 can aggravate hepatocellular carcinoma malignancy and facilitate hepatocellular carcinoma cell metastasis via activating ERK/AKT/MMP2 pathway and CCR4 can promote colorectal cancer metastasis via activating ERK/NF-κB/MMP13 pathway." (PMID 39473097, 2025).
peripheral T-cell lymphoma (17 papers, 2011 to 2025). "In a phase II study performed in Japan, 37 patients with relapsed/refractory CCR4+ peripheral T-cell lymphoma (n = 29) and MF (n = 7) received mogamulizumab at a dose of 1 mg/ kg IV once per week for 8 weeks with ORR as the primary endpoint." (PMID 31417860, 2019). "Based on these results, mogamulizumab was approved in Japan in 2014 for relapsed/refractory CCR4-positive peripheral T-cell lymphoma and cutaneous T-cell lymphoma." (PMID 31417860, 2019). "CCR4 is expressed by peripheral T-cell lymphoma and T-cell leukemia and a humanized Ab directed against CCR4 is used to treat these types of cancer." (PMID 28415693, 2017). "The anti-CCR4 antibody mogamulizumab has been shown to reduce peripheral Treg counts in patients, leading to regulatory approval for the treatment of peripheral T cell lymphomas in Japan." (PMID 27330808, 2016). "Based on gene expression profiling, Amador and colleagues recently assessed Th1 (Tbet and CXCR3) and Th2 (GATA3 and CCR4) protein expression using the IHC algorithm in cases of nodal and extranodal peripheral T-cell lymphoma, not otherwise specified (PTCL, NOS)." (PMID 38474383, 2024). "Mogamulizumab has been approved for CCR4+ ATL and for peripheral T cell lymphoma (PTCL) and cutaneous T cell lymphoma (CTCL)." (PMID 37259456, 2023). "The anti-CCR4 monoclonal antibody mogamulizumab markedly enhances antibody-dependent cellular cytotoxicity and has been approved for the treatment of patients with CCR4-positive ATL, peripheral T-cell lymphoma, and CTCL." (PMID 29915722, 2018). "Indeed, defucosylated humanized anti-CC chemokine receptor 4 (CCR4) mAbs, which exert a strong ADCC effect, were found to be effective and well tolerated as a treatment for patients with relapsed CCR4-positive ATL or peripheral T-cell lymphoma." (PMID 23651542, 2013). "MAb KM0761, is another humanized anti-CCR4 mAb that has shown promising results in CTCL animal studies and in clinical trials for refractory Adult T-cell leukemia (ATLL) and peripheral T cell lymphoma (PLCL) where good clinical activity without severe adverse side effects was seen." (PMID 22973452, 2012).
hepatocellular carcinoma (16 papers, 2014 to 2025). A malignant tumor that arises from hepatocytes. "A murine study of hepatocellular carcinoma indicated that T-regulatory cells are attracted by CCL17 through the CCR4 axis and that high CCR4 expression is positively associated with metastasis." (PMID 37686617, 2023). "Aberrant CCR4 expression in tumor cells has been associated with tumor progression and metastasis in breast cancer 150, hepatocellular carcinoma 151, and oral tongue cancer." (PMID 36118530, 2022). "CCR4 and its ligands CCL17 and CCL22 have been shown to mediate stimulatory signals for angiogenesis and tumor growth, and CCR4 blockade was associated with reduced tumor invasion and metastasis and better prognosis in some human cancer types such as hepatoma and colon cancer." (PMID 37124725, 2023). "Abundant evidences indicate that CCL17 can perform biological functions through interacting with CCR4 in a series of diseases, including tumor-promoting effects on hepatocellular carcinoma and bladder cancer." (PMID 39473097, 2025). "The authors suggested that the Wnt/β-catenin pathway downstream of CCL17/CCR4 signaling regulated the stemness of hepatocellular carcinoma cells." (PMID 36118530, 2022). "Notably, downregulated CCR4 consistently decreases the invasive capacity of hepatocellular carcinoma cells, and a CCR4 antagonist had antitumor effects in a murine model." (PMID 36555280, 2022). "CCR4 is also involved in the pathomechanism of hepatocellular carcinoma." (PMID 36555280, 2022). "Hepatocellular carcinoma cells express high levels of CCR4 153, and treating these cells with either the conditioned medium from M2 macrophages, which express higher CCL17 levels than M1 macrophages, or with exogenous CCL17, promoted survival, migration, and tumorsphere formation." (PMID 36118530, 2022). "In HCC, the up-regulation of the lncRNA HULC (hepatocellular carcinoma up-regulated long noncoding RNA) was associated with the depletion of IGF2BP1, which recognizes m6A-modified HULC molecules and recruits the CCR4-NOT complex to initiate HULC degradation." (PMID 40584291, 2025). "For instance, Tregs, which abundantly express CCR4, CCR8 and CCR10, were directed to hepatocellular carcinoma (HCC) sites, where their corresponding ligands, CCL22 and CCL28, were present, affecting the treatment outcome by evading the immune system." (PMID 40852716, 2025). "In hepatocellular carcinoma, the stability of the lncRNA highly upregulated in liver cancer (HULC) was decreased by RBPs through the recruitment of CCR4-NOT complex." (PMID 32670859, 2020).
lung carcinoma (16 papers, 2014 to 2024). "Statistical analysis revealed no considerable association between genotype/alleles frequencies of CCR4 C1014T SNP and the type of lung cancer." (PMID 25031489, 2014). "Multi-SNP analysis and haplotype deduction is required to completely eliminate the role of CCL22 and CCR4 genetic changes in susceptibility to lung cancer." (PMID 25031489, 2014). "In the current study we investigated the association between CCL22 gene polymorphism at position 16C/A, and CCR4 gene polymorphism at position C1014T and lung cancer." (PMID 25031489, 2014). "Stage III cancers had significantly higher expression of CXCL2, CD69, CCR4, and TNFRsf13c, all of which have been implicated as potential therapeutic targets in other malignancies, or in the case of CCR4, poor prognosis in lung cancer." (PMID 35881197, 2023). "Consistently, CCL22 producing osteoclasts and CCR4 expressing lung cancer cells were shown to be colocalized in bone metastases." (PMID 34064589, 2021). "It has been reported that the high expression of CCR4 level can promote tumor metastasis in lung cancer and breast cancer." (PMID 28959024, 2017). "Furthermore, high CCR4 expression in the TME correlates with poor prognosis in lung cancer patients." (PMID 37371612, 2023). "Moreover, it has been shown that miR-532-5p via inhibiting CCR4 suppresses migration and invasion of lung cancer cells." (PMID 35651789, 2022). "The results of this study demonstrates that CCL22 gene polymorphism at position 16C/A and CCR4 gene polymorphism at position C1014T, appear not to be associated with susceptibility to lung cancer." (PMID 25031489, 2014). "In the current study, the association between CCR4 single point mutation at locus C1014T with lung cancer was also not found." (PMID 25031489, 2014). "CNOT6 encodes Ccr4a protein that was a deadenylase subunit of the CCR4-Not complex, and the CNOT6 rs2453176 C>T polymorphism was related to an increased risk of lung cancer." (PMID 33251144, 2020). "CNOT3, a subunit of the CCR4-NOT complex, has recently been suggested to be overexpressed in lung cancer and involved in tumor malignancy." (PMID 37919290, 2023).
allergic asthma (14 papers, 2005 to 2025). A asthma with a basis in a pathological type I hypersensitivity reaction. "The production of chemokines, particularly CCL22, plays a crucial role in regulating the migration of CC chemokine receptor 4 (CCR4)‐expressing immune cells to the airways in type 2 inflammatory airway disorders, such as allergic asthma." (PMID 39508721, 2024). "Collectively, these results reinforce the potential application of CCR4 antagonists against allergic asthma." (PMID 33669094, 2021). "CD4+ T cells expressing CCR4 have thus been of particular interest in the pathogenesis of allergic asthma." (PMID 29507584, 2018). "For determining the potency of compounds in blocking the interaction of CCR4 in vivo, we used the ovalbumin induced allergic asthma model in mice." (PMID 29118379, 2017). "Both of these chemokines are CCR4 ligands and will attract CCR4-expressing Th2 cells to the lungs, which is essential for the development of allergic asthma." (PMID 28894452, 2017). "CCR4 is expressed by type‐2 inflammatory cells, including Th2 cells and innate lymphoid cells, which generate IL‐4, IL‐5, and IL‐13, and contribute to the etiology of allergic asthma." (PMID 39508721, 2024). "Allergic asthma is typically driven by Th2 cells that predominantly express CCR4." (PMID 33669094, 2021). "The pathogenesis of allergic asthma is driven by CCR4-expressing Th2 cells." (PMID 33669094, 2021). "A similar result has been observed in experimental allergic asthma, where the transfer of CCR4+ regulatory T cells obtained from spleens and lymph nodes, but not CCR4− regulatory T cells, attenuates eosinophilia, the production of IL-4 and IL-5, and airway inflammation." (PMID 30584243, 2018). "In conclusion, the data from this study demonstrate for the first time that compound 8a as a small molecule antagonist specifically targeting CCR4/CCL17/CCL22/CKLF1 axes effectively attenuates the allergic airways inflammation in a murine model of allergic asthma in vivo." (PMID 29118379, 2017). "On the other hand, CCR4+CD4+ T cells are clearly less frequent in ILD compared to allergic asthma." (PMID 16095529, 2005). "Therefore, antagonists targeting the interaction of CCR4 and their ligands could be attractive medicines against allergic asthma by inhibiting Th2 cell migration to inflammatory sites." (PMID 29118379, 2017). "We also determined whether these novel CCR4 antagonists could alleviate allergic asthma in a mouse." (PMID 29118379, 2017). "Of these, only CCL17 (chemokine that specifically binds and induces chemotaxis in T cells via CCR4) displayed a higher non-specific relationship with allergic asthma when compared to the value obtained for non-allergic asthma." (PMID 33936056, 2021). "Moreover, a recent single study has shown that circulating pDCs express increased levels of CCR4 and CCR10 in patients with allergic asthma." (PMID 24877070, 2014).
prostate carcinoma (14 papers, 2014 to 2024). A carcinoma that arises from epithelial cells of the prostate gland. "To evaluate whether the ligands of CCR4 are associated with prognosis in human prostate cancer, we performed in silico survival analyses using TCGA dataset." (PMID 35131860, 2022). "We searched for mRNA expression of CCL17, CCL22, CCR4, and Foxp3 in the publicly available transcriptomic dataset of human prostate cancer from TCGA PanCancer Atlas (n=493)." (PMID 35131860, 2022). "Immunohistochemistry confirmed that tumor-infiltrating Tregs expressed CCR4 in human patients with prostate cancer." (PMID 35131860, 2022). "Compared with the normal prostate, Foxp3+ Tregs and CCR4+ cells were more frequent in patients with prostate cancer." (PMID 35131860, 2022). "High mRNA expression of CCL17, CCL22, CCR4, and Foxp3 was detected in 5.0%, 3.0%, 2.2%, and 5.0% of patients with prostate cancer, respectively." (PMID 35131860, 2022). "More tumor-infiltrating CCR4+ cells were evident in dogs with prostate cancer, the density being positively correlated with the number of Foxp3+ Tregs." (PMID 35131860, 2022). "Here, we show that Tregs in the tumor microenvironment are associated with poor prognosis in dogs with spontaneous prostate cancer, and that there is a link between Treg migration and C-C chemokine ligand 17 (CCL17)–CCR4 pathway." (PMID 35131860, 2022). "Dogs with advanced prostate cancer responded to mogamulizumab, a monoclonal antibody targeting CCR4, with decreased circulating Tregs, improved survival, and low incidence of clinically relevant adverse events." (PMID 35131860, 2022). "In this study, we have shown that Foxp3+ Tregs infiltrate tumor tissues via the CCL17–CCR4 pathway, and anti-CCR4 treatment exerts an antitumor effect in dogs with advanced prostate cancer." (PMID 35131860, 2022). "CCR4 blockade leads to clinical activity and improves survival without severe toxicity profiles in a canine model of advanced prostate cancer." (PMID 35131860, 2022). "Both CCR2 and CCR4 were observed to be expressed in human prostate cancer cell lines and prostate cancer tissues; furthermore, in vitro co-culture of prostate cancer cells and macrophages resulted in increased CCL2 and CCR2 levels in prostate cancer cells." (PMID 30871130, 2019). "The fact that phosphorylation of Akt proteins was more effectively inhibited by the CCR4 antagonist than by the CCR2 antagonist also indicates the efficiency of CCR4 in prostate cancer migration and invasion." (PMID 28039457, 2017). "Inhibition of the CCL2–CCR2 or CCL17/CCL22–CCR4 axis by specific antagonists of CCR2 or CCR4 clearly showed suppression of the migration ability of prostate cancer cells." (PMID 28039457, 2017). "IHC analysis revealed a significant increase in both CCR2 and CCR4 expressions in prostate cancer cells compared with the expressions in epithelial cells in normal prostate tissues." (PMID 28039457, 2017). "Quantitative reverse transcription polymerase chain reaction (RT-PCR) showed that CCR2 and CCR4 were expressed in all prostate cancer cell lines that we checked." (PMID 28039457, 2017). "Further analyses of protein levels, including western blot and immunocytochemical staining, showed that CCR2 and CCR4 were expressed in all prostate cancer cell lines." (PMID 28039457, 2017). "CCR2 and CCR4 antagonists clearly inhibited the migration ability of prostate cancer cells, which was induced by CCL2 and CCL17/CCL22." (PMID 28039457, 2017). "We demonstrated the CCR2 and CCR4 gene and protein expressions in prostate cancer cells as well as in human prostate cancer tissues, which are novel findings for CCR4." (PMID 28039457, 2017). "In contrast, overexpression of the chemokine receptors CCR4 and CXCR4 have been associated with poor prognosis and the promotion of a variety of cancers including prostate cancer." (PMID 24466240, 2014). "We also demonstrate the therapeutic efficacy of anti-CCR4 treatment in dogs with prostate cancer." (PMID 35131860, 2022).